BDNF (brain derived neurotrophic factor)
Diseases named in the same sentence as BDNF in open-access papers (continued):
Sharing a sentence is not in itself a finding about the gene and the disease.
sleep disorder (32 papers, 2016 to 2026). A change from the patient's baseline sleeping pattern, in the hours slept and/or an alteration/dysfunction in the stages of sleep. "A case‐control study that involved patients with sleep disorders and healthy controls illustrated that BDNF serum level was associated with the progression of sleep disorders." (PMID 38491789, 2024). "Acute SD in patients with primary and secondary sleep disorders was associated with decreased serum BDNF levels." (PMID 34623740, 2021). "This study investigates whether BDNF variants and promoter I methylation may be implicated in sleep disturbances in older adults." (PMID 36737401, 2023). "Therefore, according to our previous study, we examined the association between stress and BDNF stratified by sleep disturbances: in sleep healthy subjects and those suffering from sleep disturbances." (PMID 37993570, 2023). "In addition, the association between stress and BDNF might depend on whether someone suffers from sleep disturbances or not53,71." (PMID 37993570, 2023). "Recent research has identified potential biomarkers, such as decreased serum brain-derived neurotrophic factor (BDNF) levels, which are negatively correlated with poor sleep quality and demonstrate predictive value for sleep disorders in clinical populations." (PMID 41586064, 2026). "Patients with sleep disorders often exhibit physiological characteristics such as reduced oxidative stress levels and insufficient brain-derived neurotrophic factor (BDNF) expression." (PMID 41030341, 2025). "Our findings of elevated BDNF promoter methylation associated with abnormal sleep continuity supports observations of reduced circulating BDNF levels in patients with sleep disturbances." (PMID 36737401, 2023). "Since sleep disorders, such as OSA, are highly prevalent in modern societies, their association with BDNF needs to be more extensively investigated." (PMID 36294343, 2022). "Electroacupuncture (EA) has demonstrated efficacy and safety in the treatment of sleep disorders and was shown to increase BDNF level in the brain while improving cognitive function." (PMID 34623740, 2021). "A recent clinical experiment suggested that 8 weeks of oral supplementation of H. erinaceus mycelium can improve mood and sleep disorders as determined by the circulating pro-BDNF and BDNF as biomarkers." (PMID 34865649, 2021). "Serum BDNF levels are often reduced in sleep disorders, as insomnia, probably due to increased stress, which in turn reduces neurotrophic factor levels." (PMID 32410966, 2020). "Besides, experimental and clinical findings suggest a protective role of BDNF against sleep disorders." (PMID 38491789, 2024). "Furthermore, this review showed that neurological processes, such as catecholamine and BDNF signaling pathways, can be regulated by acupuncture, which is a crucial aspect of the acupuncture mechanism in sleep disorders." (PMID 37614343, 2023). "We therefore believe that the rapid clinical improvement of patients and the subsequent rapid normalization of BDNF or the temporary overactivity of BDNF resulting from sleep disorders could mediate the development of mania." (PMID 36294388, 2022). "Similarly, peripheral BDNF concentrations were higher in patients with sleep disorders, and multiple linear regression analysis revealed that peripheral BDNF concentrations were independently correlated with PSQI scores." (PMID 34526917, 2021). "These bidirectional associations could be equally mediated by proteins, such as BDNF (brain-derived neurotrophic factors) or proinflammatory cytokines (IL-1β, TNF-α), which are involved in both pain perception and sleep disorders." (PMID 34574901, 2021). "Research by Hairston indicated that BDNF expression was abnormal in rats with sleep disorder." (PMID 28761498, 2017).
sleep disorder (continued). "BDNF regulates synaptic activity and synaptic activity has been well known; the regulation function of acupuncture on BDNF partly illustrated the pathway of tranquilizing and allaying excitement needling method treatment in patients with sleep disorder." (PMID 28761498, 2017). "People with no BDNF production have been found to have an NREM sleep disorder." (PMID 39906619, 2025). "However, it has also been suggested that BDNF is not directly correlated to a specific sleep disorder, or sleep duration, but with the proportion of sleep stages and REM sleep." (PMID 32410966, 2020). "Consequently, the presence of sleeping disorder, the amount of alcohol intake or the habit of regular exercise, variables with documented influence on BDNF level, were not involved into the final analysis (these were not significantly correlated with seBDNF in univariate models, data are not shown)." (PMID 27478486, 2016).
amnesia (31 papers, 2008 to 2026). Pathologic partial or complete loss of the ability to recall past experiences ( AMNESIA, RETROGRADE) or to form new memories ( AMNESIA, ANTEROGRADE). "Nonetheless, BDNF-ASO caused amnesia only for the similar condition, indicating that synthesis of BDNF was required only to consolidate overlapping memories." (PMID 29085903, 2017). "Finally, the amnesia caused by mRNA and protein synthesis inhibitors can be reversed by BDNF signaling reactivation following memory refresh." (PMID 34436491, 2021). "p-Coumaric acid enhances long-term potentiation, restores memory in scopolamine-induced amnesia models, and promotes neurogenesis via BDNF signaling." (PMID 41471381, 2025). "The expression levels of BDNF in the SC+GL and SC+RD amnesia groups significantly increased compared to the SC group both in the hippocampus (p < .01 in both groups) and in the cortex (p < .01 in both groups)." (PMID 38688895, 2024). "In the present study, we observed the effects of RDEO on learning and memory functions in the rat model of scopolamine‐induced amnesia, as well as the changes in AChE activity, M1 mAChR expression, and BDNF levels." (PMID 38688895, 2024). "Our data showed that RD successfully restored low levels of BDNF in a rat model of scopolamine‐induced amnesia." (PMID 38688895, 2024). "Scopolamine is reported to induce amnesia in young mice by impairing transcription of brain-derived neurotrophic factor which play a key role in control of memory development and plasticity, among other cognitive processes." (PMID 36593834, 2022). "Moosavi, Hosseini60 stated that polyphenols in DP increased BDNF expression and enhanced memory through the activation of the CREB-BDNF pathway in the SCO-induced amnesia." (PMID 34290261, 2021). "In the present study, the induction of scopolamine-induced amnesia showed suppression of BDNF and TrkB expressions in the hippocampus." (PMID 31736744, 2019). "As a molecular mechanism underlying the memory enhancing effect of GIN against SCO-induced amnesia, the expression of BDNF was examined." (PMID 29770155, 2018). "To investigate the possible mechanisms of YJT against the scopolamine injection-induced amnesia, we measured the hippocampal protein levels of AChE activity and BDNF." (PMID 29507588, 2018). "Therefore, our study demonstrated that FSJ has protective and therapeutic effects in the SCO-induced mouse model of amnesia and may be associated with improvements in hippocampal neurogenesis, in the cholinergic system, and in the signaling pathway that involves BDNF, CREB, and Akt." (PMID 26939918, 2016). "A previous study found that ginger extract contributed to the upregulation of brain-derived neurotrophic factor (BDNF) in an amnesia mouse model, which was triggered by the activation of protein kinase B/Akt as well as the cAMP-response element binding protein (CREB) signalling pathway." (PMID 37570837, 2023). "We hypothesized that induced alteration of NgR1, NgR3, LOTUS, BDNF and AMPA may underlie the antidepressant effects of ECT as well as the treatment-induced amnesia." (PMID 24244357, 2013). "Further, increased BDNF mRNA and protein levels as well as TrkB activation in the insular cortex accompany hippocampus-independent conditioned taste aversion (CTA) memory retrieval, and interfering with BDNF synthesis in this cortex after reactivation causes amnesia." (PMID 31507380, 2019). "Overall, these findings suggest that ODH has anti-amnestic potential via activation of BDNF and p-CREB and inhibition of AChE in mice with scopolamine induced amnesia." (PMID 29370115, 2018). "Fermented Curcuma longa, Asparagus officinalis, Aronia melanocarpa, and pine needle extracts improved memory dysfunction in SCO-induced amnesia models by increasing the expression of CREB (or p-CREB) and BDNF." (PMID 29770155, 2018).
amnesia (continued). "Nevertheless, our findings suggest possible mechanisms involving the Nogo system, BDNF and AMPA receptors for both the antidepressant and amnesia effects of the intervention." (PMID 24244357, 2013). "The differential spatial-specific roles of BDNF in memory consolidation and reconsolidation might provide a novel target for separately manipulating newly encoded and reactivated memories without causing universal amnesia." (PMID 23185492, 2012). "In contrast, the CB1R inverse agonist AM251 failed to reverse propranolol-induced amnesia, which was instead rescued by recombinant BDNF infusion into the hippocampus 120-min post-training." (PMID 41689307, 2026). "In summary, GE could alleviate Scop -induced amnesia in mice through promoting the cholinergic neurotransmission, enhancing antioxidant system and activating the ERK/CREB/BDNF signaling." (PMID 30369882, 2018). "Large body of evidences suggests that expression of calcium/calmodulin-dependent protein kinase II (CaMKII), brain-derived neurotrophic factor (BDNF), and calcineurin is differentially altered in the hippocampus, basolateral amygdala (BLA), and medial prefrontal cortex (mPFC) stress-induced amnesia." (PMID 26413117, 2015). "The differential and spatial-specific roles of BDNF in memory consolidation and reconsolidation suggest that dissociative molecular mechanisms underlie these processes, which may provide novel targets for manipulating newly encoded and reactivated memories without causing universal amnesia." (PMID 24137274, 2013). "Likewise, walnut protein hydrolysates could ameliorate behavioral performance, increase the expression of Nrf2, BDNF, CREB, levels of ACh, and ACh receptor in mice with amnesia." (PMID 41179368, 2025). "Therefore, upregulation of BDNF by CDRI-08 might activate Arc transcription and translation during scopolamine induced amnesia." (PMID 26413129, 2015). "For example, blockade of BDNF signaling through its TrkB receptor, or through function-blocking anti-BDNF, disrupted LTM but not STM for a conditioned IA event, whereas infusion of recombinant BDNF into hippocampus rescued IA memory from amnesia induced by glucocorticoid receptor blockade." (PMID 25071492, 2014).
cerebral infarction (31 papers, 2012 to 2025). An ischemic condition of the brain, producing a persistent focal neurological deficit in the area of distribution of the cerebral arteries. "It was recently shown that intraventricular administration of adeno-associated virus (AAV), carrying the BDNF gene, reduces the site of cerebral infarction." (PMID 30081596, 2018). "Similarly, intracerebroventricular administration of adeno-associated virus (AAV) carrying the BDNF gene reduces brain infarction." (PMID 24312581, 2013). "Our findings suggest that EVs preconditioned with memantine are capable of more effectively reversing the decrease in BDNF levels induced by cerebral infarction." (PMID 40873771, 2025). "In a rat cerebral infarction model, BDNF and TrkB were permanently reduced at the center of cerebral infarcts, while the immune response in the ischemic penumbra was increased." (PMID 35177977, 2022). "Zhang and Pardridge (2001) treated a mouse model of cerebral infarction with exogenous BDNF and observed reduced infarct volume at both 24 h and 7 days after treatment vs. control groups." (PMID 35177977, 2022). "This study testified target relationship and differential expressions between miR-206 and BDNF in the cerebral infarction model group and the meridian massage group by qPCR and WB." (PMID 36065265, 2022). "Gastrodin injection combined with deproteinization of calf serum can effectively improve neurological function score and BDNF level in patients with cerebral infarction." (PMID 35463081, 2022). "Previous studies found that EA stimulation (2/15 Hz) applied at the GV20 enhanced motor performance recovery and BDNF expression in rats with cerebral infarction." (PMID 35221914, 2022). "This showed that BDNF was protective against cerebral infarction and involved in the occurrence and development of cerebral infarction." (PMID 35177977, 2022). "This is associated with significant improvements to regional CBF, decreases in cerebral infarction volume, and an enhancement of BDNF secretion in the hippocampus." (PMID 31191223, 2019). "Brain injury was assessed in rodents and swine through the following variables: BDNF, brain infarct, GFAP, lesion volume, neurological score and rotarod and were reported in total 4, 19, 4, 7, 15, and 7 studies, respectively." (PMID 30528323, 2019). "For instance, BDNF application reduces the volume of cerebral infarction area in the middle cerebral artery occlusion (MCAo) in rodents." (PMID 30081596, 2018). "The neuroprotective effect of endogenous and exogenous BDNF is well established after brain infarction." (PMID 26682073, 2015). "Another study also found a positive correlation between motor function recovery rate and hippocampal BDNF expression after treadmill training following cerebral infarction." (PMID 26682073, 2015). "Studies have also shown that BDNF exerts neuroprotective effects against cerebral infarction by activating intercellular survival signaling pathways in transient MCAo in rats." (PMID 24606810, 2014). "On the basis of these findings, we suggest that EA at acupoints exerted its neuroprotective effects against cerebral infarction and behavioral deficits in our mild MCAo model, at least partly, through the upregulation of BDNF expression." (PMID 24606810, 2014). "We previously evaluated recovery from hemiplegia and expression of brain-derived neurotrophic factor (BDNF) using a photochemically induced cerebral infarction model of the rat." (PMID 23527298, 2013). "For example, treatment with BDNF reduces the size of brain infarction when given prior to middle cerebral artery occlusion (MCAo) in rodents." (PMID 24312581, 2013). "Another study revealed that QXTLF enhanced synaptic plasticity and functional recovery in rats with cerebral infarction by modulating the brain-derived neurotrophic factor (BDNF)/tropomyosin receptor kinase B (TrkB)/cAMP response element-binding protein (CREB) signaling pathway." (PMID 41168840, 2025).
cerebral infarction (continued). "Additionally, BDNF-hNSCs-Exo significantly inhibited inflammation and reduced the volume of cerebral infarction after injection of BDNF-hNSCs-Exo into the brains of rats." (PMID 37553595, 2023). "Moreover, additional studies have revealed that low-frequency rTMS promotes the expression of c-Fos and BDNF in the cerebral cortex of rats with cerebral infarction." (PMID 29318150, 2017). "It is possible that subjects with SCA who had silent cerebral infarctions may account for those with higher NRG-1, BDNF or PDGF-AA levels." (PMID 35935682, 2021). "Furthermore, these authors reported the activity of non-neuronal BDNF-producing cells after cerebral infarction in rat models." (PMID 23527298, 2013).
neuropathic pain (31 papers, 2011 to 2025). Chronic pain caused by damage to nerve fibers. "miR-155, on the other hand, is robustly upregulated after the activation of immune cells, including microglia, whereas BDNF expression by microglia has been implicated in the induction of neuropathic pain." (PMID 24804980, 2014). "Additionally, the spinal BDNF/TrκB signaling pathway is implicated in the induction of neuropathic pain following SNL-evoked neuropathic pain." (PMID 32906633, 2020). "In neuropathic pain, microglia-derived BDNF contributes to excitatory/inhibitory imbalance via TrkB and p75 neurotrophin receptor (p75NTR), enhancing dorsal horn excitability." (PMID 41292555, 2025). "Multiple lines of evidence suggest that BDNF primarily functions as a pro-nociceptive modulator, playing a key role in the onset and persistence of inflammatory, chronic, and/or neuropathic pain." (PMID 38785946, 2024). "This study contributes to understand the effects of tDCS in the nociceptive behavior and BDNF levels of neuropathic pain rats in development." (PMID 38188001, 2023). "Taken together, the current findings suggest that EA has analgesic effects in CCI-induced neuropathic pain, at least partly via miR-206-3p/BDNF regulation." (PMID 35719137, 2022). "On the other hand, brain-derived neurotrophic factor (BDNF) can increase the intensity of pain in rodent inflammatory and neuropathic pain models." (PMID 35061744, 2022). "In our study, BDNF levels were increased in DRG of oxaliplatin-induced neuropathic pain rat model (115.8 ± 23.4%, P = 0.047)." (PMID 31765435, 2019). "Since BDNF is known to elicit hyperalgesia and to be upregulated in a neuropathic pain model, the glial Kir4.1-BDNF system also seems to be involved in chronic pain sensitization in neuropathic pain." (PMID 30356026, 2018). "Brain-derived neurotrophic factor (BDNF) has been shown to control microglial responses in neuropathic pain." (PMID 23363775, 2013). "Chronic administration of GBP over a period of 2 weeks does not cause changes in BDNF expression in the ipsilateral dorsal horn of the lumbar spinal cord in animal models of neuropathic pain." (PMID 35875670, 2022). "We manifested that miR-30a-3p might involve the EP300-mediated BDNF activation via targeting the acetylated histone H3 and H4 on BDNF promoter in neuropathic pain." (PMID 33103739, 2020). "Meanwhile, we found that brain-derived neurotrophic factor (BDNF) is involved in neuropathic pain." (PMID 33103739, 2020). "Accordingly, this further confirmed that the therapeutic effect of 2 Hz EA on SNI-induced neuropathic pain is highly correlated with the BDNF/TrκB cascade, implying that 2 Hz EA stimulation induces the analgesic effect via blocking the BDNF/TrκB signaling pathway in the spinal cord of SNI rats." (PMID 32906633, 2020). "Accordingly, we hypothesized that 2 Hz EA stimulation may exhibit its analgesic effect by inhibiting spinal BDNF/TrκB signaling pathway-mediated central sensitization in SNI-induced neuropathic pain in rats." (PMID 32906633, 2020). "Microglial MAP kinases can be activated by IL-1β and TNF-α, inducing, via transcription factors such as NFκB, additional production of IL-1β, TNF-α, IL-6, IL-10, TGF-β, PGE2, BDNF, and cathepsin S and promoting the deleterious effects of microglial infiltration and phagocytosis in neuropathic pain." (PMID 24642655, 2014). "Microglia release BDNF in response to ATP via the activation of P2X4 receptors, which causes central sensitization by attenuating inhibitory synaptic transmission, leading to the onset of neuropathic pain." (PMID 21876755, 2011). "For example, in neuropathic pain models, SNL enhances TET1 expression in dorsal horn neurons, leading to 5-hmC enrichment at the brain derived neurotrophic factor (BDNF) promoter, which in turn increases spinal BDNF expression and neuronal excitability." (PMID 39125894, 2024).